DAB2IP (DAB2 interacting protein)
Diseases named in the same sentence as DAB2IP in open-access papers (continued):
Sharing a sentence is not in itself a finding about the gene and the disease.
prostate carcinoma (continued). "It was recently reported that knockdown of DAB2IP, a known prostate tumor suppressor gene that is often lost in aggressive prostate cancer patients, confers PC-3 cells highly migratory and metastatic properties in vitro and in vivo." (PMID 22916121, 2012). "DAB2IP, located on Chromosome 9q33, is a GTPase activating protein thought to play an important role in prostate cancer metastasis." (PMID 22400124, 2012). "DAB2IP acts as a tumor suppressor gene and is inactivated by methylation or polycomb Ezh2 complex and histone deacetylase in prostate cancer." (PMID 21144020, 2010). "miR-149-3p was aberrantly expressed in several cancers, including bladder cancer, prostate cancer, breast cancer, lung cancer and endometrial cancer, where miR-149-3p inhibited the activation of DAB2IP (Disabled-2 Interacting Protein) to enhance the cells viability and aggressiveness." (PMID 34798882, 2021). "Similarly, upregulation of miR-32 downregulates DAB2IP in prostate cancer, inducing autophagy via mTOR pathway activation and counteracting radiotherapy-induced apoptosis, thus leading to increased cancer cell survival after ionizing radiation treatment." (PMID 33096593, 2020). "DAB2IP is involved in PI3K/AKT signaling in prostate cancer and breast cancer." (PMID 30770783, 2019). "DAB2IP is a member of the RAS-GTPase-activating protein (RAS-GAP) family and is downregulated in several cancer types, including prostate cancer, bladder cancer, hepatocellular cancer, and colorectal cancer, suggesting that DAB2IP has emerged as an attractive target for cancer therapy." (PMID 29743885, 2018). "Furthermore, DAB2IP is involved in TNFα-induced apoptosis in prostate cancer cells in part by suppressing the ASK1-JNK and PI3K-AKT pathway, and in endothelial cells via inhibiting the ASK1-JNK pathway." (PMID 27036023, 2016). "We hypothesized that pretreatment DAB2IP reduction would predict worse prostate cancer‐specific survival (PCSS)." (PMID 26471467, 2015). "This current study attempted to answer our hypothesis that with longer follow up and increased sample size, pretreatment tumor status of DAB2IP would ultimately predict worse prostate cancer‐specific survival (PCSS)." (PMID 26471467, 2015). "Moreover, it was shown in prostate cancer that down-regulation of DAB2IP expression results in resistance to ionizing radiation, which initiates epithelial-to-mesenchymal transition and promotes tumor growth and metastasis." (PMID 24912918, 2014). "Furthermore, DAB2IP can prevent the progression of prostate cancer by inhibiting epithelial-to-mesenchymal transition (EMT) via Wnt-elicited β-catenin pathway." (PMID 25115390, 2014). "Inactivation of DAB2IP by promoter methylation occurs in several malignancies, including prostate and breast cancer, and it has been shown to modulate epithelial-to-mesenchymal transition and prostate-cancer metastasis." (PMID 22737080, 2012). "DAB2IP may relate to the pathogenesis of lung cancer as study have shown that in prostate cancer DAB2IP influenced the repair effectiveness of DNA double-strand breaks induced by medical exposure to ionizing radiation which is a risk factor of lung cancer." (PMID 22046421, 2011). "In prostate cancer, though activating mutations in Ras are not frequently reported, loss of DAB2IP, a Ras GTPase-activating protein (RasGAP), has been closely associated with aggressive metastatic prostate cancer." (PMID 21464902, 2011). "However, the expression level of miR-149 is increased in prostate cancer, which can enhance motility and invasiveness of cancer cells by downregulating DAB2IP and promote activation of NF-κB signaling and expression of proangiogenic factors to enhance tumor progression." (PMID 34957298, 2021). "Additionally, our results confirmed our hypothesis that DAB2IP reduction ultimately leads to significantly increased mortality due to prostate cancer." (PMID 26471467, 2015).
prostate carcinoma (continued). "Therefore, loss of DAB2IP expression facilitates EMT, leading to prostate cancer metastasis." (PMID 24073285, 2013). "The top hit compounds were also tested on the other edited prostate cancer cell line, DU145-HiBiT, and on parental non-edited DU145 cells, confirming their action on DAB2IP." (PMID 40867592, 2025). "BRCA2, DAB2IP, and the DNA-PKcs inhibitor NU7441 are prostate cancer-related markers, while the methylation of ESR1 and MYOD1 and expression of SEPT9 correlate with radiotherapy response in cervical cancer." (PMID 40277781, 2025). "Until now, only a few target genes have been studied in depth to clarify the regulatory network of EZH2 in prostate cancer, including CDH1, DAB2IP, ADRB2." (PMID 31636385, 2020). "DAB2IP is transcriptionally down regulated in a variety of tumors and is involved in epithelial to mesenchymal transition (EMT) and prostate cancer metastasis." (PMID 31666665, 2019). "Recent studies provide evidence that down-regulation of DAB2IP is mediated by polycomb EZH2 and histone deacetylase in prostate cancer." (PMID 26336990, 2015). "Although DAB2IP is often epigenetically down regulated by EZH2 activation in many tumors, we defined a novel pathway of functionally inactivating DAB2IP in prostate cancer cells through Akt activity." (PMID 24912918, 2014). "For this study, we used a modified human prostate cancer (PCa) cell line, PC3, in which we knocked down a tumor suppressor protein, DAB2IP (PC3-KD)." (PMID 23525451, 2013). "Our previous study also confirmed that DAB2IP could promote EMT and metastasis in prostate cancer by inhibiting proteasome degradation of HIF1α through targeting PROX1 transcription." (PMID 35342346, 2022). "Analogously, a cell non-autonomous effect was described by us for miR-149-3p in prostate cancer; this miRNA is secreted by cancer cells and can reduce DAB2IP levels in endothelial cells (ECs), potentially remodeling the tumor microenvironment." (PMID 33096593, 2020). "DAB2IP (DOC2/DAB2 interactive protein), a member of the RAS-GTPase-activating protein (RAS-GAP) family, is downregulated in several cancer types, such as prostate cancer, bladder cancer, hepatocellular cancer, and colorectal cancer." (PMID 29743885, 2018). "Moreover, in prostate cancer, EZH2 can repress the expression of tumor suppressors such as DAB2IP, p16 (CDKN2A), CDK4, E-cadherin (CDH1), MSMB, Ras (KRAS), NF-κB (NFKB1), EMT regulator." (PMID 27835578, 2016). "DAB2IP also inhibits epithelial mesenchymal transition (EMT) and metastasis in prostate cancer." (PMID 26336990, 2015). "The DAB2IP pathway is an important potential target for improving the treatment of multiple malignancies (not just prostate cancer) and enhancing multiple modalities (not just radiation therapy)." (PMID 26471467, 2015). "As a partial answer to this question, we and others found that treatment with conditioned medium from breast and prostate cancer cells induces DAB2IP downregulation in receiving non-transformed cells, stimulating proliferation, migration, and tube-forming ability of endothelial cells." (PMID 38902547, 2024). "Theoretically, a mouse having no ability to produce DAB2IP might simultaneously develop hallmark signs of CAD (inflammation, athero- and arteriosclerosis) and protection against the development of prostate cancer." (PMID 34140969, 2021). "Interestingly, DAB2IP expression is modulated by EZH2, a histone methyltransferase forms part of the polycomb repressor complex, and has been proposed as a potential drug target in prostate cancer." (PMID 22400124, 2012).
breast carcinoma (20 papers, 2012 to 2025). "This study offers new insight into a subset of Luminal A breast cancer shown to be at higher risk of recurrence with loss of DAB2IP." (PMID 39418101, 2024). "We first studied the association between survival rate and low DAB2IP expression in patients with ER+ cancer broadly and then specifically in patients with Luminal A breast cancer." (PMID 39418101, 2024). "Here we show that DAB2IP protein expression is lost in some grade 2/stage II or higher ER+ breast tumors, thereby suggesting that DAB2IP loss in ER+ breast cancer contributes to a more aggressive stage of disease." (PMID 39418101, 2024). "Low DAB2IP expression in ER+ breast cancer cells was associated with increased proliferation, enhanced stemness phenotypes, and activation of IKK, the upstream regulator of the transcription factor NF-κB." (PMID 39418101, 2024). "We also identified SRSF1, an RNA-binding protein strongly linked with breast cancer progression and metastasis, to be upregulated in DAB2IP-low Luminal A tumors." (PMID 39418101, 2024). "This suggests that loss of DAB2IP expression plays a key role in regulating NF-κB targets, contributing to altered splicing in Luminal A breast cancer." (PMID 39418101, 2024). "Mining the The Cancer Genome Atlas (TCGA) breast cancer RNA-Seq dataset revealed that low expression of the RasGAP DAB2IP was associated with a significant decrease in relapse-free survival in patients with Luminal A breast cancer." (PMID 39418101, 2024). "To extend and confirm the RNA studies, we tested DAB2IP protein expression and association with clinical grade by performing IHC staining on ER+ breast cancer tissue microarrays (TMAs)." (PMID 39418101, 2024). "For breast cancer, research on DAB2IP loss is largely limited to the work of Cichowski and colleagues who studied its loss within the Luminal B TCGA cohort." (PMID 39418101, 2024). "The second is that, although infrequent, deleterious mutations in DAB2IP are found in tumors, in particular colorectal and breast cancers." (PMID 38902547, 2024). "We show here that approximately 25%–30% of Luminal A breast cancers exhibit low DAB2IP expression and that this is associated with poor relapse-free survival and a significantly higher ROR score." (PMID 39418101, 2024). "We also identified 71 genes bound by NFKB2 that were upregulated with low DAB2IP in both the ChIP-Seq and TCGA RNA-Seq datasets, which were enriched in terms associated with breast cancer." (PMID 39418101, 2024). "Our results demonstrate the consequence of loss of DAB2IP in ER+ breast cancer, specifically focused on Luminal A breast cancer, and provide insight into underlying mechanisms that lead to the aggressiveness of this subset of tumors." (PMID 39418101, 2024). "Taken together, these observations led us to investigate the association between the NF-κB signaling pathway and the loss of DAB2IP in the Luminal A breast cancer subtype." (PMID 39418101, 2024). "In the gene enrichment analysis, we observed that the DAB2IP-low Luminal A breast cancer subtype is associated with established CSC gene signatures." (PMID 39418101, 2024). "Using murine breast cancer (BC) xenograft models, we evaluated the association with DAB2IP and chemoresistance." (PMID 36536485, 2022). "The combined loss of RASAL2 and DAB2IP in a subset of luminal B breast cancers results in epithelial–mesenchymal transition (EMT)." (PMID 31799194, 2019). "IKK/NF-κB pathway activation by loss of DAB2IP in the Luminal A breast cancer subtype." (PMID 39418101, 2024). "Taken together, Luminal A breast cancer with low DAB2IP expression is associated with increased cancer hallmark characteristics, including cell proliferation and metastasis, which may be due to increased NF-κB and enhanced ER signaling." (PMID 39418101, 2024).
breast carcinoma (continued). "Loss of DAB2IP increases the proliferation and migration of Luminal A breast cancer cells." (PMID 39418101, 2024). "Furthermore, low DAB2IP expression is associated with advanced, more aggressive Luminal A breast cancers, as indicated by more CNAs." (PMID 39418101, 2024). "Similarly, DAB2IP promoter methylation and expression downregulation were identified to be associated with breast cancer lymph node metastasis." (PMID 31627186, 2019). "We concluded that Thio, Sal, and Ube can increase endogenous DAB2IP in at least three different cell lines, representing both prostate and breast cancers." (PMID 40867592, 2025). "We determined the effect of NF-κB activation in DAB2IP-low Luminal A breast cancer by profiling RELA, RELB, and NFKB2 genomic binding and gene expression using ChIP-Seq in stable DAB2IP knockdown and control T47D cells." (PMID 39418101, 2024). "In this study, we found that DAB2IP inhibited glucose uptake under hypoxia conditions in breast cancer cells by suppressing HIF-1α signals." (PMID 38862467, 2024). "Further experimentation is needed to determine the mechanisms whereby DAB2IP expression is reduced in breast cancer." (PMID 39418101, 2024). "TCGA breast cancer data also show a similar decrease in DAB2IP expression at the RNA level with increasing T-stage in patients with ER+ luminal breast cancer, particularly significant in T2 tumors." (PMID 39418101, 2024). "Next, to investigate the effect of loss of DAB2IP on NF-κB target genes, we selected SRSF1, and BIRC5, which are known to play important protumorigenic roles in breast cancer." (PMID 39418101, 2024). "DAB2IP is widely reported to be a tumor suppressor that acts as a scaffold protein to suppress tumor malignancy in breast cancer." (PMID 38862467, 2024). "To analyze DAB2IP expression across breast cancer subtypes, we utilized TCGA breast cancer RNA-Seq data from 1,082 breast tumors." (PMID 39418101, 2024). "Deleting the PER domain abrogated the DAB2IP-related inhibitory effects on glucose uptake, intracellular ATP production, and lactic acid production in breast cancer cells." (PMID 38862467, 2024). "Here, we explored Luminal A breast cancer and showed that low DAB2IP expression leads to poorer outcomes, similar to what is described for patients with Luminal B breast cancer." (PMID 39418101, 2024). "Intriguingly, they found that RASAL2 is frequently silenced together with DAB2IP in high-grade luminal B breast cancers." (PMID 38902547, 2024). "Perhaps the most convincing study was published by Wang Min and colleagues, who found that conditional DAB2IP depletion in ECs is sufficient to boost tumor growth and metastasis in mouse xenograft models of melanoma and breast cancer." (PMID 38902547, 2024). "The epithelial cell adhesion molecule EPCAM — a transmembrane glycoprotein overexpressed particularly in tumor-initiating cells (TICs) in various cancers, including breast cancer — was also more highly expressed in DAB2IP-low Luminal A tumors." (PMID 39418101, 2024). "In breast cancer, Cichowski and colleagues found that DAB2IP cooperates with another RasGAP family member, RASAL2, to limit metastasis in ER+ breast cancer." (PMID 38902547, 2024). "To test if loss of DAB2IP signaling contributes to tumor cell proliferation in Luminal A breast cancer cells, we performed DAB2IP knockdown in the Luminal A cell line T47D." (PMID 39418101, 2024). "Since copy number alterations (CNAs) are generally associated with cancer progression, we then examined the number of CNAs based on DAB2IP status in the Luminal A breast cancer TCGA cohort." (PMID 39418101, 2024). "Specifically, breast cancer cells with a defective disabled homolog 2-interacting protein (DAB2IP) are often aggressive and resistant to radiation." (PMID 36499000, 2022).
breast carcinoma (continued). "In luminal B breast cancer, due to promoter hypermethylation, disabled homolog 2-interacting protein (DAB2IP) is selectively suppressed." (PMID 31799194, 2019). "The restoration of DAB2IP expression by 5-acetazolamide-2-cytosine deoxyriboside (5azaDC, DNA demethylating agent) supported the epigenetic regulation of breast cancer progression." (PMID 31627186, 2019). "In a luminal B mammary tumor mouse model, the loss of RASAL2 enhanced metastasis and, using this model, 60% of primary tumors spontaneously lost DAB2IP, which also increased metastasis." (PMID 31799194, 2019). "DAB2IP acts as a tumor suppressor gene, and is inactivated by methylation in prostate and breast cancers." (PMID 29221435, 2017). "DAB2IP promoter methylation is frequently present in human breast cancer as well which plays a key role in DAB2IP inactivation and lymph node metastasis." (PMID 26471467, 2015). "We hypothesize that p38 contributes to certain low-DAB2IP oncogenic phenotypes in ER+ breast cancers." (PMID 39418101, 2024). "For example, pathway analysis reveals the association of highly expressed genes in DAB2IP-low ER+ tumors with STK33, a protumorigenic kinase that increases proliferation in breast cancer cells and has been associated with advanced colorectal and pancreatic malignancies." (PMID 39418101, 2024). "Furthermore, DAB2IP knockdown promoted proliferation in Luminal A breast cancer cells and promoted stemness in both Luminal A and Luminal B cells." (PMID 39418101, 2024). "Similar to reports regarding genetic changes that promote more aggressive ER+ breast cancer phenotypes, we found that the differential gene expression pattern in Luminal A DAB2IP-low tumors correlates closely with genes expressed in Luminal B and HER2 tumors, irrespective of their DAB2IP status." (PMID 39418101, 2024). "Notably, promoter hypermethylation of RASAL2 and DAB2IP was identified in aggressive luminal B breast cancer." (PMID 31627186, 2019). "DAB2IP encodes a member of the RAS GTPase-activating gene family and has been reported to act as a tumor suppressor: its inactivation by promoter methylation occurs in several malignancies, including prostate and breast cancer." (PMID 25466287, 2014). "Here we have defined the exact breakpoints of six previously identified deletion alleles disrupting the CYP2C19, CDH19, CASP3, DCLRE1C, DAB2IP and ITGA9 genes, respectively, and evaluated their association with breast cancer risk and disease subtype using a Northern Finnish case–control cohort." (PMID 25466287, 2014). "Furthermore, IKK is known to phosphorylate substrates that are distinct from traditional NF-κB signaling; thus, these pathways may be relevant to DAB2IP-low luminal breast cancers." (PMID 39418101, 2024). "Furthermore, although not significant, TCGA Luminal A RNA-Seq data indicate lower DAB2IP expression in patients with T2 and T4 Luminal A breast cancer compared with normal tumors." (PMID 39418101, 2024).